MIR500B (microRNA 500b)
Synonyms: hsa-mir-500b; mir-500b
Gene: MicroRNA gene on chromosome X (50,010,672 to 50,010,750, forward strand). Ensembl gene ENSG00000239057.
Gene Ontology:
Biological process: miRNA-mediated post-transcriptional gene silencing
Cellular component: RISC complex
Homologues: Orthologues: chimpanzee ptr-mir-500-2 (100% identical), guinea pig MIR500B (90% identical). Paralogues in human: MIR500A (90% identical), MIR501 (87% identical), MIR502 (85% identical).